HMGA2 (high mobility group AT-hook 2)
Diseases named in the same sentence as HMGA2 in open-access papers (continued):
Sharing a sentence is not in itself a finding about the gene and the disease.
mesenchymal tumors (28 papers, 2007 to 2025). "There is evidence that augmented expression of a high mobility group AT-hook 2 (HMGA2) is associated with common benign mesenchymal tumors and rare aggressive cancers." (PMID 37576599, 2023). "The description of miRNA-mediated HMGA protein regulation begins with the finding that chromosomal abnormalities in the regions 12q15 and 6p21.3 were associated with the aberrant expression of either HMGA2 or HMGA1 in several benign mesenchymal tumours." (PMID 31979076, 2020). "HMGA2 affects mesenchymal differentiation and ES cell proliferation and tissue‐specific overexpression of full‐length HMGA2 causes mesenchymal tumors." (PMID 28500786, 2017). "HMGA2 upregulation has been associated with the growth of several mesenchymal tumors, including LM." (PMID 35884847, 2022). "HMGA2 has been implicated in DNA translocations in lipomas and mesenchymal tumors." (PMID 33668453, 2021). "However, causative mechanisms of mesenchymal tumorigenesis by HMGA2-induced alteration of chromatin structure is yet to be delineated for most mesenchymal tumors." (PMID 32365712, 2020). "HMGA2 has been implicated mainly in benign and malignant mesenchymal tumors Nevertheless, increased expression of HMGA2 in oral squamous cell carcinoma has been linked to epithelial-mesenchymal transition, whereby epithelial cells acquire mesenchymal characteristics." (PMID 17222355, 2007). "A strong HMGA2 overexpression, even in benign mesenchymal neoplasms, can enable a clear-cut distinction of neoplastic from non-neoplastic tissues." (PMID 40518465, 2025). "The overexpression of HMGA2 is observed in a variety of mesenchymal tumors across multiple organ systems, including those in the head and neck, lungs, bones, breast, and female reproductive organs." (PMID 38473181, 2024). "It is noteworthy that HMGA2 is also involved in gene fusion in a variety of mesenchymal tumors, including lipoma, uterine leiomyoma, aggressive angiomyxoma, pulmonary chondroid hamartoma, soft tissue chondroma, and dedifferentiated liposarcoma." (PMID 38792018, 2024). "In different mesenchymal tumors, chromosomal rearrangements and breakpoints can generate truncated HMGA2 mRNA transcripts, which are devoid of the 3′-UTR regions, thus altering miRNA-mediated regulation of HMGA2 expression." (PMID 34439740, 2021). "Both full-length and 3′UTR truncated HMGA2 in transgenic mice develop benign mesenchymal tumors, including breast fibroadenomas and salivary gland adenomas." (PMID 33668453, 2021). "Our data compilation reveals that the most common translocation partners of HMGA2 in mesenchymal tumors are chromosomes 1–3, with a preponderance of intragenic chromosome 12 aberrations." (PMID 32365712, 2020). "We reviewed cytogenetic analyses of mesenchymal tumors and found that most chromosomal abnormalities occurred by balanced chromosomal rearrangements involving HMGA2 locus 12q13–15." (PMID 32365712, 2020). "In this section, we explore evidence for HMGA2-induced pathogenesis in benign and malignant mesenchymal neoplasms." (PMID 32365712, 2020). "The nature of the chromosomal rearrangements and resulting mRNA HMGA2 transcript also differ by mesenchymal tumor type." (PMID 32365712, 2020). "These chromosomal translocations have been reported as the genetic mechanisms necessitating HMGA2 misexpression in mesenchymal tumors." (PMID 32365712, 2020). "HMGA2 has been documented to regulate adipogenesis and mesenchymal differentiation and promote benign mesenchymal tumors." (PMID 31885559, 2019). "HMGA2 rearrangements are well known in several mesenchymal tumors, conversely little is known about the expression and function of HMGA1 in these tumors." (PMID 29980789, 2018). "Chromosomal rearrangements involving the region around the HMGA2 gene have been reported in several benign mesenchymal tumors." (PMID 29487700, 2018).
mesenchymal tumors (continued). "Another piece of evidence for the importance of the interaction between HMGA2 and miRNAs is the many disrupted forms of HMGA2, due to rearrangements of chromosomal band 12q15, that are seen in different benign mesenchymal tumors." (PMID 28423547, 2017). "High levels of Hmga2 have been observed in several mesenchymal tumors and various human carcinomas, where it is expressed mainly detected in the cell nucleus." (PMID 28415789, 2017). "HMGA2 is of particular interest in ESFT because its overexpression is associated with both benign and malignant mesenchymal tumors and because it has been shown to regulate mesenchymal stem cell genes." (PMID 21853155, 2011). "Deregulation, typically through chromosomal rearrangements, of HMGA2 has an important role in the development of several mesenchymal neoplasms." (PMID 19508721, 2009). "Notably, this overexpression is a common feature in uterine smooth muscle tumors and other mesenchymal neoplasms of gynecological origin, where specific molecular and genetic alterations result in the increased expression of HMGA2." (PMID 38473181, 2024). "The HMGA2 gene immediately appeared to be more complex than the HMGA1 gene, essentially due to its length and the presence of a very large intron involved in rearrangements, leading to truncated or chimeric HMGA2 transcripts especially in benign mesenchymal tumours." (PMID 31979076, 2020). "This may suggest that HMGA2 misexpression is a relatively rare event in malignant mesenchymal tumors." (PMID 32365712, 2020). "Consistently, misexpression of full-length Hmga2 induces benign mesenchymal tumors in mice." (PMID 32365712, 2020). "Given the multiple binding sites for let-7 in many chromosomal 3’ UTR loci, it is possible that HMGA2 is mis-expressed when the relative abundance of HMGA2 mRNA transcripts suffice to bind available let-7 and sustain HMGA2 re-expression in benign mesenchymal tumors." (PMID 32365712, 2020). "This seemingly limited influence of let-7 in directly regulating HMGA2 misexpression could be more reflective of its cooperative roles with other translation regulatory networks in the ontogenesis of mesenchymal tumors." (PMID 32365712, 2020). "As LAM pathogenesis is characterized by benign tumors with differentiating characteristics towards a mesenchymal phenotype, we postulated that the oncogenic triangle involving LIN28-let-7-HMGA2 observed in most mesenchymal tumors might account for the tumorigenic pathway employed by HMGA2 in LAM." (PMID 32365712, 2020). "In this review, we will explore these mechanisms by which HMGA2 induces epithelial and mesenchymal tumorigenesis, and discuss the gene’s role in lymphangioleiomyomatosis, a rare pulmonary mesenchymal neoplasm of unknown etiology that is often a clinical manifestation of tuberous sclerosis." (PMID 32365712, 2020). "In this review, we deepen our understanding of HMGA2 pathogenicity by exploring the mechanisms by which HMGA2 misexpression and ectopic expression induces mesenchymal and epithelial tumorigenesis respectively and distinguish the pathogenesis of benign from malignant mesenchymal tumors." (PMID 32365712, 2020). "The HMGA2 gene, coding for an architectural transcription factor involved in mesenchymal embryogenesis, is frequently deranged by translocation and/or amplification in mesenchymal tumours, generally leading to over-expression of shortened transcripts and a truncated protein." (PMID 20576167, 2010). "As all forms of HMGA2 transcript exhibit similar transformative potential, it can be hypothesized that a single regulatory regimen could chiefly govern the misexpression of these different transcript types and their propensity to drive the pathogenesis of benign mesenchymal tumors." (PMID 32365712, 2020).
mesenchymal tumors (continued). "Unlike the preponderance of studies performed on benign mesenchymal tumors, only a few preliminary studies have determined the role of HMGA2 misexpression in malignant mesenchymal tumors such as well differentiated liposarcomas and osteosarcomas." (PMID 32365712, 2020). "Most frequently, chromosomal break points truncate the HMGA2 3’ UTR in mesenchymal tumors and can thus prevent the docking of let-7 to its binding sites and the canonical repression of HMGA2 expression in differentiated mesenchymal tumors." (PMID 32365712, 2020). "In contrast, the misexpression of full length, chimeric or truncated HMGA2 mRNA transcripts in differentiated benign mesenchymal tumors derived from abnormal chromosomal breaks governs mesenchymal tumorigenesis irrespective of the nature of the HMGA2 gene product." (PMID 32365712, 2020). "HMGA2 nuclear immunoreactivity, even if not specific, is present in most cases of DAM and could be useful in distinguishing it from other mesenchymal tumors; however this was not tested in any of the cases occurring in pregnancy." (PMID 37444513, 2023).
Obesity (27 papers, 2008 to 2026). Accumulation of substantial excess body fat. "HMGA2 knock-out in mice results in diet-induced obesity while certain HMGA2 mutations lead to unusually small-sized mice." (PMID 40518465, 2025). "The let-7 family is involved in adipocyte differentiation by targeting the high-mobility group AT-Hook 2 (HMGA2) protein, which reduces adipose tissue in obese leptin-deficient mice, suggesting, once again, a role for leptin and obesity in CRC." (PMID 34199293, 2021). "In contrast, a high-fat diet can induce the HMGA2 expression in adipose tissues and cause obesity in wild-type and leptin-deficient mice." (PMID 32466162, 2020). "The involvement of Hmga2 in fat tissue differentiation is also stressed by the observation that Hmga2 deficiency renders the mouse resistant to diet-induced obesity and mitigates the effect of leptin deficiency." (PMID 31963852, 2020). "The Let-7 family has been shown to act as a pro-adipogenic factor targeting high-mobility group AT-Hook 2 (HMGA2) protein, which reduces fat mass in obese leptin-deficient mice suggesting, once again, a role for leptin and obesity in CRC." (PMID 31207998, 2019). "BMI z-score increased with all tested obesity risk variant alleles ranging from 0.087 (rs1042725 HMGA2) to 0.303 (rs6013029 CTNNBL1)." (PMID 23339409, 2013). "The HMGA2 gene (High-Mobility Group AT-Hook 2) encoding protein contains three AT-hook DNA-binding motifs, acts as a transcription regulator and is involved in adipogenesis and diet-induced obesity." (PMID 37628596, 2023). "For instance, HMGA2 is linked to obesity, diabetes, stem cell youth, and oncogenesis." (PMID 35212375, 2022). "The disruption of the Hmga2 gene caused a dramatic reduction in obesity of the leptin-deficient mice (Lepob/Lepob) in a gene-dosage-dependent manner: Hmga2+/+ Lepob/Lepob mice weighed over three times more than Hmga2-/- Lepob/Lepob animals, and the weight of Hmga2+/- Lepob/Lepob mice was in between." (PMID 32466162, 2020). "Hmga2−/− mice show a reduction in fat tissue, due to lower proliferation of pre-adipocyte cell precursors; significantly, Hmga2 expression is reactivated in adult fat tissue of wild type mice upon high fat diet, and in leptin-deficient genetic models of obesity." (PMID 31963852, 2020). "Interestingly, the HMGA2 gene generates a truncated form of HMGA2 (HMGA2Tr), which is associated with tumorigenesis and obesity." (PMID 29736175, 2018). "Also apoE deficient mice show high levels of cholesterol and develop spontaneous atherosclerosis while mice with partial or complete deficiency of high-mobility group A2 protein (Hmga2) are able to resist diet-induced obesity." (PMID 18959802, 2008). "For example, our recent genome wide association study (GWAS) of tooth emergence identified associations with variants in genes that have been implicated in obesity, HMGA2 and BMP4, suggesting a hitherto unrecognised link may exist between tooth emergence and obesity." (PMID 24823714, 2014). "Hmga2 has been shown to be crucial for preadipocyte proliferation and adipogenesis, with Hmga2 gene silencing resulting in the attenuation of adipocyte maturation and overexpression contributing to a murine obesity phenotype." (PMID 38516887, 2024). "Due to the importance of HMGA2 in adipogenesis and tumorigenesis, HMGA2 is considered a potential therapeutic target for anticancer and anti-obesity treatments." (PMID 35212375, 2022). "Knockout of the HMGA2 gene in mice demonstrated the involvement of this gene in diet-induced obesity." (PMID 36292658, 2022). "Previous results showed that HMGA2 is a potential therapeutic target of anticancer and anti-obesity drugs by inhibiting its DNA-binding activities." (PMID 33139812, 2020). "With the identification of HMGA2 as a potential target for the treatment of obesity and cancer, the next step is to search for chemical compounds that prevent HMGA2 binding to its target DNA sequences." (PMID 33139812, 2020).
Obesity (continued). "Due to the importance of HMGA2 in adipogenesis and tumorigenesis, HMGA2 is considered a potential therapeutic target for anticancer and anti-obesity drugs." (PMID 32466162, 2020). "It is this disordered-to-ordered transition that has implicated HMGA2 as a protein actively involved in many biological processes, with abnormal HMGA expression linked to a variety of health problems including diabetes, obesity, and oncogenesis." (PMID 35212375, 2022). "In addition, HMGA2 has transcriptional regulating factors which play a role in adipogenesis and fat storage, inducing obesity." (PMID 25852736, 2015). "In addition, ECGC showed therapeutic potential in obesity inhibiting white and beige 3T3-L1 and D12 preadipocyte growth by upregulated miR-let-7a and subsequent high-mobility group AT-hook 2 (HMGA2) suppression and inhibiting the MAPK7 pathway by increased miR-143 levels." (PMID 38201989, 2024). "As a multifunctional regulator, IGF2BP2 is probably involved in the pathogenesis of PCOS through different pathways and its upstream regulator, HMGA2, is attributed to initate the dysfunction of cell proliferation, which is also related to T2DM and obesity." (PMID 35293050, 2022).
pituitary adenomas (27 papers, 2003 to 2026). "Overexpression of HMGA2 is a hallmark of various tumors, including pituitary adenomas, and is associated with highly malignancy." (PMID 25548562, 2014). "Heightened expression of high-mobility group protein A2 (HMGA2) is associated with human and murine pituitary adenomas, and HMGA2 is over-expressed in the pituitary tumors of the TG mice used in this study." (PMID 23226476, 2012). "Similarly, the significant inverse association was also detected between let-7 and HMGA2 in esophageal cancer, retinoblastomas and pituitary adenomas." (PMID 25884389, 2015). "RPSAP52 (Ribosomal Protein SA Pseudogene 52) is an antisense lncRNA for the HMGA2 gene, with an overexpression that is critical in developing pituitary adenomas." (PMID 40362297, 2025). "Of note, HMGA1 and HMGA2 are key proteins in the development of pituitary adenomas; indeed, they induce pituitary cell transformation through the enhancement of the activity of E2F1 and other factors." (PMID 34484116, 2021). "Accordingly, another work described the relationship between miR-16 and HMGA2 in pituitary adenoma cells." (PMID 31979076, 2020). "The oncogenic role of PTTG1 and HMGA2, two oncogenes previously suggested to play a relevant role in human pituitary adenoma formation, has been analyzed in transgenic mice." (PMID 25136513, 2014). "Transgenic mice expressing high levels of the HMGA2 transgene in all tissues (by using the cytomegalovirus promoter) developed mixed growth hormone/prolactin cell pituitary adenomas with high penetrance (85% of female animals) by 6 months of age." (PMID 25136513, 2014). "HMGA2 was frequently upregulated in pituitary adenomas including PRL, ACTH, FSH/LH, or null cell adenomas but relatively rare in GH and mixed GH/PRL adenomas." (PMID 25548562, 2014). "A recent report suggests a role for progesterone in the growth of pituitary adenomas via concomitant activation of oncogenes HMGA2 and E2F1 and the downregulation of the retinoblastoma (RB) protein." (PMID 23226476, 2012). "Hmga2-induced pituitary adenomas exhibit >5-fold downregulation of Sox2 compared with normal pituitary tissue." (PMID 20668695, 2010). "In fact, transgenic mice expressing high levels of the HMGA2 gene develop pituitary adenomas secreting prolactin and growth hormone." (PMID 16914062, 2006). "By co-immunoprecipitating HMGA2 and pRB in pituitary adenomas developed by HMGA2 mice, we demonstrated the interaction between the two proteins occurring in the tumor." (PMID 16914062, 2006). "This review focuses on recent data that explain the mechanism by which HMGA2 induces the development of pituitary adenomas in mice." (PMID 16914062, 2006). "Does the afore-reported HMGA2-dependent molecular events result in enhanced E2F1-dependent gene transcription in pituitary adenomas?" (PMID 16914062, 2006). "Our data demonstrate that E2F1 activation is a crucial step required for the onset of pituitary adenomas in HMGA2 transgenic mice." (PMID 16914062, 2006). "Since HMGA2 amplification and overexpression has been detected also in human pituitary adenomas, we retain that E2F1 activation plays a critical role also in the human pituitary pathology." (PMID 16914062, 2006). "Overexpression of HMGA2 gene leads to the onset of prolactin and GH-hormone induced pituitary adenomas in mice, suggesting a critical role of this protein in pituitary tumorigenesis." (PMID 16914062, 2006). "A clue to this issue was, however, provided by a recent report that transgenic mice carrying the HMGA2 gene developed pituitary adenomas." (PMID 14647145, 2003). "It has been found highly overexpressed in pituitary adenomas, where HMGA2 overexpression plays a central role in the tumorigenesis of pituitary gland, and in anaplastic thyroid carcinomas that express very high HMGA2 levels (D’Angelo, unpublished observations)." (PMID 25859543, 2015). "HMGA2 is another oncogene that has been found to be overexpressed in pituitary adenomas." (PMID 25136513, 2014).